CRP (C-reactive protein)
Diseases named in the same sentence as CRP in open-access papers (continued):
Sharing a sentence is not in itself a finding about the gene and the disease.
COVID-19 (continued). "The significant association of pericardial effusion with increased CRP levels indicates that pericardial inflammation plays an important role in the development of pericardial effusion in COVID-19 patients." (PMID 36013560, 2022). "Lymphocyte percent and CRP have been reported to be associated with the severity and outcome of COVID-19." (PMID 35021153, 2022). "This study showed that older age, longer length of hospital stays, diabetes mellitus, hypertension, obesity, smoking history, and higher neutrophil, C-reactive protein, and procalcitonin are value risk factors for co-infection in COVID-19 patients." (PMID 36365001, 2022). "Old age, male sex, underlying comorbidities, and elevated lactate dehydrogenase, C-reactive protein, and ferritin levels are established risk factors in relation to disease severity in COVID-19." (PMID 36464717, 2022). "In fact, the inflammatory response in patients with severe COVID-19 is particularly striking: elevated levels of inflammatory markers (such as C-reactive protein, ferritin and various cytokines), which are associated with poor outcomes." (PMID 35173744, 2022). "Clinical studies indicate that statins decrease serum CRP levels, an inflammatory biomarker and risk factor for adverse COVID-19 outcomes." (PMID 35811982, 2022). "Various studies have reported a raised CRP and lymphopenia in patients with COVID-19, and this is associated with more severe illness and patients requiring longer hospital admissions." (PMID 36106205, 2022). "In our study, CRP, IL-6, and IL-2R were independent risk factors for severe events in all enrolled COVID-19 patients in the univariate analysis, and CRP was an independent risk factor for severe events in the multivariate analysis." (PMID 36033814, 2022). "Although number of studies have already shown the association of COVID-19 severity with CRP and D-dimer levels in blood, there are limited studies done on Bangladeshi populations." (PMID 36568370, 2022). "Obesity is also an indicator for severity of COVID-19 symptoms, with high levels of C reactive protein (CRP) indicating strong critical illness risk." (PMID 35348641, 2022). "There is a possibility that pro-inflammatory neutrophils and C-reactive protein provoke “cytokine storm” associated to endothelialitis in COVID-19 infected cancer patients." (PMID 36059615, 2022). "Association analysis revealed that Alloprevotella in COVID-19 patients was positively correlated with the level of the inflammation biomarker C-reactive protein." (PMID 36350127, 2022). "Colchicine treatment decreased CRP levels and COVID-19 severity, with dimer levels, all-cause mortality and mechanical ventilation remaining seemingly unaffected." (PMID 35381033, 2022). "Several studies showed that patients with NAFLD have intrinsically higher C-reactive protein (CRP) and IL-6 serum concentrations, which are both associated with COVID-19 severity." (PMID 35743825, 2022). "A meta-analysis of 20 studies that included 4843 patients with COVID-19 found a fourfold increased risk of poor outcomes in patients who had elevated CRP levels (>10 mg/L)." (PMID 36366539, 2022). "A total of 88 potential explanatory variables were included in the model, which covered SA and CRP values; demographic characteristics; baseline comorbidities; and clinical, radiological, and other analytical COVID-19-associated variables." (PMID 35740416, 2022). "Different biomarkers, including D-dimer, lactate dehydrogenase (LDH), C-reactive protein (CRP), serum ferritin, and procalcitonin levels, are elevated in COVID-19 patients and are associated with disease severity and clinical outcomes." (PMID 35559257, 2022). "CRP and COVID-19 severity were inversely associated with Δ-TC, Δ-LDL-C, and Δ-HDL-C (p < 0.05 for all associations)." (PMID 35743420, 2022). "CRP levels display a positive relationship with COVID-19 severity and have been demonstrated to predict the risk of thrombosis." (PMID 36466841, 2022).
COVID-19 (continued). "C-reactive protein (CRP) can be used as a diagnostic marker reflecting the severity and prognosis of COVID-19, and the levels of CRP are helpful to differentiate between viral and bacterial infections." (PMID 36514048, 2022). "In summary, this study identified 28 indicators (such as age, LDH, CRP, and lymphocytes) associated with critical illness of patients with COVID-19." (PMID 35677769, 2022). "In another report, a maximum CRP serum concentration of >100 mg/L was associated with either progressive or severe COVID-19 with a mortality of up to 59% vs. 4% in the mild group (<100 mg/L)." (PMID 35407564, 2022). "Several systematic reviews have reported that higher CRP and D-dimer levels were associated with more severe COVID-19, muscle weakness, and exercise intolerance." (PMID 36362805, 2022). "A characteristic problem occurring in COVID-19 is excessive elevations of pro-inflammatory cytokines (e.g. IL-6 and CRP) which are associated with worse clinical outcomes." (PMID 36263035, 2022). "Our study showed that features that were previously associated with COVID-19 severity in patients with cancer, such as low albumin, higher CRP, and neutrophils, remain discriminatory in patients who present with different variants." (PMID 36010932, 2022). "In patients with COVID-19, elevated serum CRP levels are also highly linked to venous thromboembolism, acute renal damage, critical illness, and in-hospital fatality." (PMID 36562867, 2022). "An increasing body of evidence suggests that risk factors for COVID-19-related mortality include older age, higher severity of illness scores, higher C-reactive protein level, lower lymphocyte counts, secondary infection and comorbidities such as diabetes." (PMID 36389149, 2022). "High CRP levels have been noted in COVID-19 patients and have been associated with severe COVID-19, the need for ICU-level care, and in-hospital mortality." (PMID 35251855, 2022). "Growing research data suggests that the severity of COVID-19 is linked with higher levels of inflammatory mediators, such as cytokines, chemokines, tumor necrosis factor, C-reactive protein, ferritin, and D-dimers." (PMID 36431254, 2022). "A study determined that patients with CRP levels higher than 41.8 mg/L were at increased risk of severe COVID-19." (PMID 36550575, 2022). "The association between COVID-19 and FVIIa-AT levels remained significant after adjustment for sex, age, C-reactive protein, renal function, fibrinogen, prothrombin time and activated partial thromboplastin time." (PMID 36428852, 2022). "As in the general population, CRP and D-dimer levels were associated with a significantly higher risk of death amongst COVID-19 patients." (PMID 35053983, 2022). "Differently, as far as our model, we have observed an indirect path between EMO and SE and teachers’ perception of the impact of COVID-19 through teachers’ risk perception of contracting SARS-CoV-2 (CRP)." (PMID 36141916, 2022). "A recent study showed similar results and that high serum CRP levels were associated with a more severe disease course in COVID-19 patients." (PMID 35676519, 2022). "Our previous studies have shown that plasma CRP level is positively associated with severity of pneumonia in COVID-19 patients." (PMID 35592303, 2022). "Among these COVID-19 patients, higher circulating CRP is associated with a higher rate of adverse events, such as venous thromboembolism events, acute kidney injury, and higher in-hospital mortality." (PMID 35204599, 2022). "In this small, single-center retrospective study, indexes modeling systemic inflammation and derived from the commonly performed CBC with differential showed better association with evolution of illness than CRP in patients admitted with COVID-19." (PMID 35733873, 2022). "Systemic inflammation, as measured by CRP, is strongly associated with critical illness and in-hospital mortality in COVID-19." (PMID 35741183, 2022).
COVID-19 (continued). "For initial appropriate treatment in the early stages of the disease, CRP levels can be used to identify patients with early-stage COVID-19 at risk of severe disease development and the risk of hospitalization, especially in older children." (PMID 36676040, 2022). "A meta-analysis of 5350 patients showed that elevated CRP was associated with an increased composite poor outcome (respiratory rate (RR)=1.84) and in the severe COVID-19 (RR=1.41) subgroup." (PMID 36060343, 2022). "Eventually, we found that teachers’ perception of risk of contracting SARS-CoV-2 (CRP) was positively, directly associated with teachers’ perception about the impact of COVID-19 on teaching (β = 0.19; p < 0.001)." (PMID 36141916, 2022). "Evidence has shown that CRP is significantly associated with the severity and prognosis of excessive inflammatory responses, such as pneumonia resulting from a complication of COVID-19." (PMID 35736249, 2022). "The early diagnostic tools for COVID-19 were based on clinical assessment along with an entire blood panel, especially inflammatory markers such as C-reactive protein, erythrocyte sedimentation rate, and D-dimer." (PMID 35233327, 2022). "Elevated CRP was associated other indicators of severity of the COVID-19 hospitalization including, supplemental oxygen and intravenous dexamethasone." (PMID 35646997, 2022). "Acute liver injury (ALI) during systemic inflammation caused by COVID-19 corresponds to increased c-reactive protein (CRP) levels, elevated interleukin-6, and high ferritin." (PMID 36676691, 2022). "Higher consumption of fruits, vegetables, and fiber was inversely linked with COVID-19 severity, clinical symptoms, hospitalization and convalescence duration, and CRP concentrations." (PMID 36245547, 2022). "IL-6, CRP, and IL-10 and have also been associated with disease severity amongst COVID-19 patients, correlating with severe clinical outcomes and fatality." (PMID 36268187, 2022). "A characteristic problem occurring in coronavirus disease 2019 (COVID-19) are excessive elevations of pro-inflammatory cytokines such as interleukin-6 (IL-6) and C-reactive protein (CRP) which are associated with worse clinical courses." (PMID 36263035, 2022). "In patients already diagnosed with a severe form of COVID-19, our research team recently identified a high-risk CRP concentration cut-off; a value above 23 mg/L is associated with a negative vital prognosis." (PMID 35888173, 2022). "Univariate tests always identified CRP as one of the most informative players in the classification of COVID-19 risk and severity and this is in accordance with a great deal of evidence from the literature." (PMID 35563218, 2022). "Patients in CA/HQ group had higher age, higher body mass index (BMI), more existence of current comorbidities, and increased levels of WBC, LDH and CRP, all of which were closely associated with critical illness in COVID-19 patients." (PMID 35507600, 2022). "High levels of CRP are associated with the development of severe disease, and they are correlated with pulmonary lesions at the early stage of COVID-19." (PMID 36477474, 2022). "Alongside elevated routine blood test parameters (CRP, fibrinogen), soluble uPAR serum levels were independently associated with more severe lung damage in COVID-19 patients." (PMID 36555850, 2022). "Some laboratory factors including leukocytosis, lymphopenia, elevated CRP, elevated ferritin, haematuria and proteinuria were also associated with COVID-19 AKI; which are reported 100, 72.2, 92.7, 88.9, 61.8 and 97.4%, respectively." (PMID 35445048, 2022). "COVID-19 is a systemic inflammatory disease, and we identified several inflammatory markers and acute phase reactants as risk, including C-reactive protein, procalcitonin, and ferritin." (PMID 35715729, 2022). "Our data analyses demonstrate that older age, dyspnea, high CRP, and lymphopenia are associated with an oxygen requirement among the COVID-19-affected hospitalized patients." (PMID 35683357, 2022).
COVID-19 (continued). "IL-6 has been known to drive CRP production primarily in the liver and as a driver of the COVID-19 cytokine storm associated with poor COVID-19 outcomes." (PMID 35510030, 2022). "This study disclosed that retinal involvement is mainly observed in patients with mild to moderate COVID-19 and is associated with elevated serum levels of fibrinogen, CRP, ferritin, and LDH." (PMID 36177323, 2022). "In the present study, COVID-19 positive AP patients were associated with a higher level of CRP and lower level of amylase and lipase, which confirmed a more severe systemic inflammation condition for these groups of patients." (PMID 36338951, 2022). "Eventually, we found that teachers’ perception of risk of contracting SARS-CoV-2 (CRP) was positively, directly associated with teachers’ perception about the impact of COVID-19 on social relationships (β = 0.23; p < 0.001)." (PMID 36141916, 2022). "A study also examined the immunological status in COVID-19-TB cases, i.e., increased C-reactive protein (CRP), d-dimers, ferritin, neutrophils, lymphocytes, cytokine storm, and chemokines have been linked to COVID-19 severity and patient mortality." (PMID 35784278, 2022). "Compared to other routine laboratory tests, it was reported that CRP level was significantly associated with COVID-19 severity." (PMID 35891270, 2022). "Univariate analysis indicated that severe COVID-19 was associated with significantly higher levels of C-reactive protein and D-dimer in blood, as well as the lower arterial partial pressure of oxygen." (PMID 36118230, 2022). "For patients hospitalized with COVID-19, those living with one or more people had an increased association with mortality, they also exhibited higher CRP indicating increased disease severity suggesting they delayed seeking care." (PMID 33999142, 2022). "The most severe period of COVID-19 was considered when maximum oxygen support was required and predictors associated with poor prognosis, namely CRP, procalcitonin, ferritin, and D-dimer were at the highest values." (PMID 36415243, 2022). "When data analysis approaches were used to uncover patterns and essential characteristics in the data, C-reactive protein, platelets, and D-dimers were determined to be the most associated to COVID-19 severity prediction." (PMID 35013702, 2022). "It was observed that, in the early stages of COVID-19, CRP levels were found to be strongly linked with the diameter of lung lesions and the severity of illness." (PMID 36267156, 2022). "Vitamin D can reduce the CRP levels and hence negatively modulate the inflammatory cytokine storm caused by COVID-19." (PMID 36611352, 2022). "High CRP is seen in majority of patients with COVID-19 with higher concentrations associated with severity of COVID-19 and it does not necessarily help identify bacterial superinfection." (PMID 35500008, 2022). "Elevation in circulating CRP levels in the context of COVID-19 has been shown to be associated with VTE." (PMID 36177015, 2022). "COVID-19 pathogenesis heavily relies on the inflammatory response, while ferritin, CRP, and D dimers are associated with mortality in COVID-19 patients." (PMID 36560587, 2022). "In the hypertensive group, age, diabetes mellitus, heart disease, smoking, glycemic control before admission, C-reactive protein, lactate dehydrogenase, lymphocytes, and D-dimer were significantly associated with COVID-19 progression and mortality." (PMID 36366507, 2022). "For example, the d-dimer levels, CRP, and neutrophil-to-lymphocyte ratio have been recognized to be associated with a worse prognosis in patients with COVID-19." (PMID 36136824, 2022). "C-reactive protein and age have been previously associated with COVID-19 severity and have been suggested as predictors of COVID-19 progression." (PMID 35806866, 2022).
COVID-19 (continued). "Another study found reduced gut microbiota richness in COVID-19 patients six months following infection, and this was associated with increased levels of serum C reactive protein (CRP, an inflammation marker to indicate infection) and severity of disease." (PMID 36297092, 2022). "Patients with COVID-19 with a vitamin D deficiency/insufficiency had higher levels of CRP, ferritin, LDH, glucose, and D-dimer at the time of hospitalization, compared to the vitamin D sufficient group (all p < 0.05)." (PMID 35337103, 2022). "In hospitalized older adults with COVID-19, tomographic pulmonary involvement > 50%, anemia, vitamin D below 40 ng/mL, and CRP above 80 mg/L were independent risk factors for progression to SRF/MV." (PMID 35172759, 2022). "Chronic lung conditions, chronic heart conditions, hemoglobin level, RBCs count, and CRP level were entered into a multivariate regression analysis to identify risk factors/predictors for moderate-to-severe COVID-19." (PMID 35151286, 2022). "Baseline anti-SARS-CoV-2 IgG levels have been associated with CRP levels in COVID-19 patients, suggesting persistence of an unresolved inflammation status." (PMID 36531241, 2022). "The main aim of this study was to examine the association of Nrf2 and HO-1 in COVID-19 patients with the disease severity and the markers of the hyperinflammatory response (C-reactive protein-CRP, IL-6, ferritin)." (PMID 36422196, 2022). "On admission, C-reactive protein levels have been rather associated with the extent of lung damage and the severity of illness in the early stages of COVID-19." (PMID 35160039, 2022). "There is a study of 196 COVID-19-positive patients that showed that cTnI (≥21 ng/L) is a better prognostic value for 30-day all-cause mortality in comparison with CRP, LDH and D-Dimer." (PMID 35162207, 2022). "This study performed in a Mexican population indicates that comorbidities such as: T2DM, hypertension and obesity, as well as elevated levels of glucose, IL-6, LDH and CRP are associated with the COVID-19 severity." (PMID 35464048, 2022). "Increased levels of IL-6 and C-reactive protein (CRP) are associated with a worse outcome from COVID-19, suggesting that inflammation contributes as a critical mediator to the heightened mortality of those patients." (PMID 35359931, 2022). "Our score stratifies the mortality risk of hospitalized patients with COVID-19 based on only four variables: age, oxygen saturation, C-reactive protein and creatinine." (PMID 36304183, 2022). "Higher CRP values constitute a biomarker for a severe disease course, are included in a widely-used clinical risk score for mortality of COVID-19, and associate with neutralizing IFN-AABs along with lower lymphocyte counts in severely affected patients." (PMID 35511314, 2022). "The main factor causing CRP generation and high levels of IL-6, which are connected to liver damage in COVID-19, is IL-6 generated by T cells, macrophages, and monocytes in response to the activation of the inborn and adaptive immune systems." (PMID 35928369, 2022). "Along with the risk genes screened in lasso regression, Charlson score, ferritin, D-Dimer, CRP, and procalcitonin are screened as risk factors for severe COVID-19." (PMID 36052061, 2022). "In a study of 213 COVID-19 survivors, both the CRP levels and LOS were associated with weight loss registered approximately three weeks after discharge, but in multivariable models, only LOS remained significantly associated with weight loss." (PMID 36145141, 2022). "Several systematic reviews and meta-analyses have confirmed that older age, pre-existing CVD, higher troponin T concentration, higher C-reactive protein, and lower albumin are associated with increased mortality among patients hospitalized with COVID-19." (PMID 35837356, 2022).